CSF1R (colony stimulating factor 1 receptor)
Diseases named in the same sentence as CSF1R in open-access papers (continued):
Sharing a sentence is not in itself a finding about the gene and the disease.
experimental autoimmune encephalomyelitis (3 papers, 2019 to 2025). An autoimmune demyelinating disease of the central nervous system that is produced experimentally in animals by the injection of homogenized brain or spinal cord in Freund's adjuvant. "CSF1R antagonism was previously shown to mitigate experimental autoimmune encephalomyelitis (EAE) severity by other groups, and this was initially attributed to microglia depletion." (PMID 38643194, 2024). "CSF1R antagonism was previously shown to mitigate clinical severity in experimental autoimmune encephalomyelitis (EAE)." (PMID 38643194, 2024).
Granuloma (3 papers, 2021 to 2025). A compact, organized collection of mature mononuclear phagocytes, which may be but is not necessarily accompanied by accessory features such as necrosis. "The synergistic activation of CSF1R and IL4R pathways in granuloma-associated macrophages likely contributes to the persistence and expansion of these lesions while promoting tissue remodeling and fibrosis, ultimately impacting cardiac function." (PMID 40521183, 2025). "Here, we show that aberrantly increased monocytopoiesis gives rise to granulomas in a sarcoidosis model, in which Tsc2, a negative regulator of mTORC1, is conditionally deleted in CSF1R-expressing macrophages (Tsc2csf1rΔ mice)." (PMID 38147536, 2024). "In the context of CS granulomas, our findings of enhanced CSF1R expression suggest that robust CSF1R signaling may create a microenvironment conducive to the accumulation of M2 macrophages." (PMID 40521183, 2025). "The concurrent expression of Acetyl-H3K9, Chi3l1, CSF1R, IL4R, TGFß, and Jak3/Stat6 in granulomas of CS further reinforces macrophages towards M2 polarization, thereby leading to anti-inflammatory states and fibrosis." (PMID 40521183, 2025). "The concurrent expression of Acetyl-H3K9, Chi3l1, CSF1R, IL4R, TGFß, and Jak3/Stat6 in granulomas of cardiac sarcoidosis promotes the polarization of macrophages toward the M2 phenotype, facilitating anti-inflammatory conditions and driving fibrotic processes." (PMID 40521183, 2025). "Our upstream pathway analysis of CSF1R identified IL4R as a regulated gene, corroborating the literature linking interleukin-4 receptor alpha (IL4RA) and interleukin-13 receptor alpha 1 (IL13RA1) signaling to granuloma." (PMID 40521183, 2025).
inflammatory breast carcinoma (3 papers, 2018 to 2024). An advanced, invasive breast adenocarcinoma characterized by the presence of distinct changes in the overlying skin. "In inflammatory breast cancer (IBC) cells, the colony stimulating factor (CSF)-1/ receptor tyrosine kinase of CSF-1 (CSF-1R) axis has a functional role in hybrid E/M phenotype development and metastasis." (PMID 33207810, 2020).
intestinal cancer (3 papers, 2021 to 2025). "In clinical trials, colony stimulating factor 1 receptor inhibits were used to target tumor-associated macrophages, such as intestinal cancers." (PMID 40677714, 2025). "Apart from the opposing effects of Mir34a and Csf1r on proliferation, apoptosis and STAT3 signaling, their antagonistic effects on the tumor-environment and intestinal cancer stem cells might also be responsible for the compensatory effect of deleting both genes." (PMID 36147476, 2022).
intracerebral hemorrhage (3 papers, 2021 to 2025). A cerebrovascular disorder characterized by bleeding into one or both cerebral hemispheres including the basal ganglia and the cerebral cortex. "Depletion of microglia by CSF1R inhibitors, such as PLX3397 and PLX5622, was also associated with improved cognitive performance in experimental mouse models of AD, intracerebral hemorrhage, and irradiation-induced memory deficits." (PMID 33402167, 2021). "Importantly, Astragaloside IV likely prevents the proliferation and migration of microglia/macrophages after intracerebral hemorrhage (ICH) by binding its transformed products to CDC42, PTK2, and CSF1R in C57 BL/6 mice model." (PMID 41049135, 2025).
intrahepatic cholangiocarcinoma (3 papers, 2022 to 2024). A carcinoma that arises from the intrahepatic bile duct epithelium in any site of the intrahepatic biliary tree. "Durvalumab combined with CSF-1R inhibitor SNDX-6352 improved overall survival (OS) in previously treated intrahepatic cholangiocarcinoma patients without causing any serious adverse effects, indicating the great potential of the CSF-1R inhibitor immunotherapy." (PMID 39065562, 2024). "Johns Hopkins Sidney Kimmel Comprehensive Cancer Center Conducts a Secondary Clinical Trial of Durvalumab (MEDI4736) combined with CSF-1R Inhibitor (SNDX-6532) following Chemo or Radio-Embolization for Patients With Intrahepatic Cholangiocarcinoma (NCT04301778)." (PMID 36275770, 2022).
invasive breast carcinoma (3 papers, 2021 to 2024). A carcinoma that infiltrates the breast parenchyma. "It is found that CSF‐1‐positive cancer cells colocalize with abundant CSF‐1R‐positive TAMs in invasive breast cancer, and the CSF‐1/CSF‐1R axis is significantly correlated with a higher grade, basal‐like phenotype, and lymph node metastasis." (PMID 33463063, 2021).
liposarcoma (3 papers, 2019 to 2025). A usually painless malignant tumor that arises from adipose tissue. "A phase Ib study has explored the combination of durvalumab with DCC-3014 (vimseltinib), a selective inhibitor of CSF1R, in 13 patients with advanced STS (7 leiomyosarcoma, 2 UPS, 2 DDLPS, 1 synovial sarcoma and 1 liposarcoma)." (PMID 37190214, 2023). "Anti-CSF1R and anti-CCL2 blocking antibodies in combination with chemotherapy are in phase I/II clinical trials in pancreatic, breast, and liposarcoma cancers." (PMID 31878276, 2019).
lung squamous cell carcinoma (3 papers, 2022 to 2023). "Existing research has suggested that high mRNA expression of C1QC and CSF1R is associated with immunosuppression in the lung squamous cell carcinoma tissue microenvironment and worsen patient survival outcomes." (PMID 36992705, 2023). "CSF1R inhibitors have been evaluated in a variety of tumors, including lung squamous cell carcinoma." (PMID 36969873, 2023).
lupus nephritis (3 papers, 2016 to 2022). Glomerulonephritis in the context of systemic lupus erythematosus. "Furthermore, accumulating evidence suggested that the CSF-1R pathway played a crucial role in chronic immune disorders such as RA, Sjogren’s syndrome (SS) and lupus nephritis (LN)." (PMID 28036035, 2016). "Elevated levels of CSF1 in serum, urine, and kidneys are correlated with the activity of lupus nephritis, and CSF1R inhibition could deplete macrophages and ameliorate kidney injury by decreasing proteinuria and blood urea nitrogen and improving renal histopathology." (PMID 35601837, 2022).
malignant glioma (3 papers, 2020 to 2024). A grade III or grade IV glioma arising from the central nervous system. "Encouragingly, a clinical trial has reported that the combination of anti‐PD‐1 and anti‐CSF‐1R therapies may provide a durable clinical benefit for malignant glioma patients (ClinicalTrials.gov identifier: NCT02526017)." (PMID 32678519, 2020). "In addition, one clinical trial has already reported that dual PD-1 and CSF-1R blockade may provide anti-tumor effects which are durable for malignant glioma patients (ClinicalTrials.gov identifier: NCT02526017)." (PMID 38370418, 2024).
malignant meningiomas (3 papers, 2021 to 2023). "Intervention with an anti-CSF1/CSF1R antibody was found to normalize the tumor microenvironment, indicating that targeting the CSF1/CSF1R axis might be a potential treatment for malignant meningiomas." (PMID 35712491, 2022).
myelogenous leukemia (3 papers, 2013 to 2020). "We also conducted a cellular phosphorylation assay of CSF-1R and the downstream signaling molecules Erk and Akt using a CSF-1-dependent murine myelogenous leukemia cell line (M-NFS-60) and CSF-1-differentiated mouse BMDMs treated with 3D185 or PLX3397." (PMID 31438996, 2019). "In the “acute phase myeloid leukemia signaling” pathway, two genes were upregulated: spleen focus-forming virus proviral integration 1 (Sfpi1 or PU.1) and colony stimulating factor 1 receptor (Csf1r)." (PMID 24063402, 2013).
osteosclerosis (3 papers, 2021 to 2024). Abnormally high bone density. "Individuals with loss-of-function alleles at the CSF1R locus almost completely lose microglia, the Mφs of the brain, and have deficiencies in skeletal development and osteosclerosis." (PMID 39544929, 2024). "He had unique metadiaphyseal splaying and osteosclerosis, vertebral end‐plate osteosclerosis, and cortical thinning of long bones but no mutation was detected of SLC29A3, TNFRSF11A, TCIRG1, LRRK1, or CSF1R associated with DSS." (PMID 35991533, 2022). "The reversal of osteosclerosis and expansion of the hematopoietic niche in the long bones likely requires the generation of CSF1R-dependent osteoclasts and resident osteomacs that were replenished in the BMT recipients." (PMID 34081701, 2021).
pigmentary orthochromatic leukodystrophy (3 papers, 2015 to 2025). "CSF1R gene mutations have been reported to cause hereditary diffuse leukoencephalopathy with spheroids (HDLS) and pigmentary orthochromatic leukodystrophy (POLD), both of which involve genetically-driven diffuse white matter lesions." (PMID 40893935, 2025). "The few recently reported families with CSF1R mutations had been previously labelled “hereditary diffuse leukencephalopathy with axonal spheroids” (HDLS) and “pigmentary orthochromatic leukodystrophy” (POLD), disorders which now appear to form a disease continuum." (PMID 25975230, 2015).
prostate tumors (3 papers, 2009 to 2025). "Phenocopying ASH1L depletion, the blockade of CSF1R significantly suppressed the outgrowth of prostate tumors in the bone." (PMID 40394007, 2025). "Mouse xenograft experiments showed that CSF-1R expression promoted the aggressiveness of prostate tumor cells." (PMID 36555673, 2022).
renal carcinoma (3 papers, 2012 to 2021). A carcinoma arising from the epithelium of the renal parenchyma or the renal pelvis. "In IPA, however, male-biased genes were most significantly enriched for genes linked to renal cancer, including the well established renal cancer gene CSF1R." (PMID 24438232, 2014). "Together, these findings confirmed the relationship of PTP4A3 to immune cell infiltration and CD79A, CSF1R, INOS, COX2, STAT5A, FOXP3 and CCR8 in KIRP, suggesting an important immune regulation role of PTP4A3 in the renal cancer microenvironment." (PMID 34630392, 2021).
adenoma (2 papers, 2022). A neoplasm arising from the epithelium. "Taken together, deletion of Csf1r largely reversed the effects of Mir34a loss on infiltration by fibroblasts, immune cells and bacteria in adenomas." (PMID 36147476, 2022). "Remarkably, the up-regulation of factors involved in EMT, stemness, Wnt signaling and extracellular matrix components in Mir34a-deficient adenomas and/or tumoroids was largely abrogated by co-deletion of Csf1r." (PMID 36147476, 2022). "In tumoroids derived from Csf1r-deficient and Csf1r/Mir34a-deficient adenomas, moderate transcriptome changes with lower numbers of differentially regulated genes were observed." (PMID 36147476, 2022). "Tumor-associated fibroblasts were increased within adenomas in Mir34a-deficient adenomas, whereas deletion of Csf1r resulted in their decrease." (PMID 36147476, 2022). "The size of adenomas was significantly larger in Mir34a-deficient and smaller in Csf1r-deficient ApcMin/+ mice when compared to Csf1rfl/fl;Mir34afl/fl;ApcMin/+ mice." (PMID 36147476, 2022). "Remarkably, the up-regulation of predicted Mir34a targets in Mir34a-deficient adenomas was largely abrogated by co-deletion of Csf1r." (PMID 36147476, 2022). "The expression of Csf1r was up-regulated in Mir34a-deficient adenomas and pri-Mir34a expression was increased in Csf1r-deficient adenomas on the mRNA and protein levels." (PMID 36147476, 2022). "Indeed, tumoroids derived from Mir34a-deficient adenomas displayed an increase in formation rate and mean size, whereas tumoroids derived from Csf1r-deficient adenomas formed at a decreased rate and were smaller." (PMID 36147476, 2022). "Next, we analyzed whether the Mir34aΔIEC adenoma signature, mature miR-34a expression and CSF1R expression is associated with HALLMARK, KEGG, as well as TF expression and TF target signatures in human CR tumors or CRC cell lines." (PMID 36147476, 2022). "Therefore, the enhanced frequency of stem cells observed in Mir34a-deficient adenomas and normal intestinal crypts, was dependent on the increased expression of Csf1r." (PMID 36147476, 2022). "Interestingly, Lgr5, which was up-regulated in Mir34a-deficient adenomas and down-regulated in Csf1r-deficient adenomas, is not only a stem cell marker, but also potentiates Wnt/β-catenin signaling." (PMID 36147476, 2022). "Furthermore, FISH with the universal eubacteria-specific probe (EUB338) revealed that Mir34a-deficient adenomas displayed more bacterial infiltration, whereas less bacterial infiltration was observed in Csf1r-deficient adenomas." (PMID 36147476, 2022). "In Csf1r-deficient adenomas, rather moderate changes in gene expression with 28 significantly up- and 26 significantly down-regulated genes were observed when compared to adenomas from control mice." (PMID 36147476, 2022). "Therefore, Csf1r is required for the recruitment of fibroblasts in Mir34a-deficient adenomas." (PMID 36147476, 2022). "However, in adenomas from Csf1r/Mir34a-deficient mice ApcMin/+ mice only 15 genes were significantly up- and 17 genes were down-regulated, indicating that the gene expression changes observed in Mir34a-deficient adenomas were largely abrogated by the concomitant deletion of Csf1r." (PMID 36147476, 2022). "Furthermore, CSF1R expression positively correlated with the majority of the analyzed gene signatures, which largely reflected the associations found for the Mir34aΔIEC adenoma signature." (PMID 36147476, 2022). "In addition, we performed NGS analyses of tumoroids derived from Mir34a- and/or Csf1r-deficient adenomas in order to identify cell autonomous changes in gene expression, which are not potentially confounded by interactions of tumor cells with the tumor-microenvironment, as in the adenomas." (PMID 36147476, 2022). "Next we used Gene Set Enrichment Analyses (GSEA) to identify pathways that are differentially regulated in adenomas and tumoroids dependent on their Mir34a and Csf1r status." (PMID 36147476, 2022).
adenoma (continued). "In order to obtain functional evidence for Mir34a/Csf1r mediated regulation of stemness in adenomas, we performed a tumoroid formation assay." (PMID 36147476, 2022). "Here, ApcMin/+ mice with intestinal-epithelial cell (IEC)-specific deletions of Mir34a showed increased formation of adenomas and decreased survival, whereas deletion of Csf1r decreased adenoma formation and increased survival." (PMID 36147476, 2022). "Notably, concomitant Mir34a and Csf1r deletion resulted in unchanged numbers of fibroblasts within adenomas." (PMID 36147476, 2022). "Furthermore, we provide genetic evidence that this regulation occurs in vivo, since Mir-34a and Csf1r displayed reciprocal repression in murine intestinal epithelium and derived adenomas." (PMID 36147476, 2022). "Consistent with the finding that activation of CSF1R induces STAT3 phosphorylation (p-STAT3) in CRC cell lines 21, the frequency of cells displaying STAT3 activation was decreased in adenomas of Csf1rΔIEC;ApcMin/+ mice, whereas deletion of Mir34a increased the number of p-STAT3-positive tumor cells." (PMID 36147476, 2022).
anaplastic large cell lymphoma (2 papers, 2015 to 2019). Anaplastic large cell lymphoma (ALCL) is a rare and aggressive peripheral T-cell non-Hodgkin lymphoma, belonging to the group of CD30-positive lymphoproliferative disorders, which affects lymph nodes and extranodal sites. "HRS cells in cHL and, with the exception of three cases of anaplastic large cell lymphoma, the neoplastic cells in NHLs, lacked detectable CSF1R protein." (PMID 26066800, 2015).
angiosarcoma (2 papers, 2014 to 2021). A malignant tumor arising from the endothelial cells of the blood vessels. "Our results show that cells with high CSF-1R expression enriched from hemangiosarcoma and angiosarcoma cell lines are more drug resistant than cells with low expression of the receptor." (PMID 25295160, 2014). "We present the finding that cells with high CSF-1R expression are more drug resistant than cells with low levels of CSF-1R expression in hemangiosarcoma and angiosarcoma cell lines." (PMID 25295160, 2014). "ABCA3 expression appeared to be low across a population of cells with high CSF-1R expression enriched from hemangiosarcoma cell lines when expression was examined using microarray anlaysis (J-H." (PMID 25295160, 2014). "We performed cell enrichment studies from canine hemangiosarcoma and human angiosarcoma cell lines to generate cell populations with high or low CSF-1R expression." (PMID 25295160, 2014). "The addition of CSF1R inhibitors to standard chemotherapy or anti-angiogenic therapy may be an attractive option in the treatment of angiosarcoma that should be further investigated." (PMID 33580206, 2021). "For this study, we demonstrate that both hemangiosarcoma and angiosarcoma cells with high expression of CSF-1R are more drug resistant than their CSF-1R low-expressing counterparts, indicating a shared mechanism for the observed treatment failures and subsequent drug resistance." (PMID 25295160, 2014). "These similarities suggest that the myeloid-endothelial cell phenotype in hemangiosarcoma may represent a viable target for therapeutic intervention, and more specifically, targeting of CSF-1R." (PMID 25295160, 2014). "Although the hemangiosarcoma and angiosarcoma cell lines showed similar drug resistance mechanisms and these populations could be enriched by targeting CSF-1R expression, the cell surface marker expression profiles differed between species." (PMID 25295160, 2014). "Here, we show that cell populations enriched for the myeloid marker, CSF-1R, are highly drug resistant in hemangiosarcoma and angiosarcoma, and this resistance may be mediated through drug sequestration within cellular lysosomes." (PMID 25295160, 2014). "Cell surface expression levels of CSF-1R were determined for the canine hemangiosarcoma cell lines COSB and DD-1 and the human angiosarcoma cell line AS5 by flow cytometry." (PMID 25295160, 2014). "We demonstrated that cells with high CSF-1R expression enriched from hemangiosarcoma and angiosarcoma cell lines are more drug resistant than cells with little or no CSF-1R expression." (PMID 25295160, 2014).
Aphasia (2 papers, 2021 to 2023). An acquired language impairment of some or all of the abilities to produce or comprehend speech and to read or write. "Speech disorders are frequently observed in CSF1R-ALSP with complex underpinnings involving language disturbances (aphasia in up to 42%), articulation disorders (dysarthria in up to 54%), and not infrequently, both." (PMID 37349768, 2023).
Autoimmunity (2 papers, 2014 to 2025). The occurrence of an immune reaction against the organism's own cells or tissues. "Star 27 should enable a reduction in FLT3-associated inflammation and autoimmunity while allowing KIT and CSF1R to compensate with classical DC maintenance." (PMID 25531068, 2014).
bone tumors (2 papers, 2020 to 2025). "Immunofluorescence staining not only verified the depletion of total TAMs (both F4/80+CD206+ and F4/80+CD206-) in the bone tumors after CSF1R blockade but confirmed the suppressing effects of ASH1L inhibition on pro-tumoral TAMs (F4/80+CD206+) in the bone niche." (PMID 40394007, 2025). "As OSA is begins in cells that form bones, whether CSF1R have some specific role in the immune microenvironment of bone tumors." (PMID 32850346, 2020).